MITF (melanocyte inducing transcription factor)
Diseases named in the same sentence as MITF in open-access papers (continued):
Sharing a sentence is not in itself a finding about the gene and the disease.
melanoma (continued). "Besides MITF, several high penetrance genes involved in telomere lengthening (such as TERT) or telomere maintenance play a role in familial melanoma predisposition, as well as other genes, such as BAP1, POT1, ACD, and TERF2IP." (PMID 32605315, 2020). "RANKL does not drive tolerance to MAPK inhibition through pathway re‐activation as has commonly been observed, but rather via an increase in MITF expression similar to the TNF‐α mediated increase in MITF that occurs when macrophages are co‐cultured with melanoma cells." (PMID 31323160, 2020). "Several lines of evidence indicate that metabolic changes regulate MITF levels and thus may impact on melanoma immunogenicity." (PMID 33276788, 2020). "Indeed, we observed that osteoblast‐CM induced phosphorylation of p65 in melanoma cells within hours and this correlated with increased MITF protein levels." (PMID 31323160, 2020). "Furthermore, the supernatant of MITF-negative melanoma cells reduces MITF expression in positive cells." (PMID 33276788, 2020). "For instance, treatment of BRAF-mutant melanomas with BRAF inhibitor, vemurafenib, or with MEK inhibitor, selumetinib, leads to microphthalmia-associated transcription factor (MITF) signalling and elevated expression of the mitochondrial master regulator, PGC-1α." (PMID 33092283, 2020). "Reduced MITF expression generates invasive melanomas, with metastasis-promoting properties." (PMID 33202765, 2020). "Furthermore, MITF, which is amplified in up to 20% of melanomas, with higher incidence among metastatic melanoma samples, was more highly expressed in TPC2 KO cells." (PMID 32846966, 2020). "Our analyses with immune‐poor melanomas stratified by MITF immunostaining suggested transcriptional upregulation of β‐catenin‐dependent canonical Wnt signaling pathway along with the upregulation of c‐Myc in the MITF‐positive group." (PMID 32147909, 2020). "Importantly, the expression of Rec was downregulated upon knocking down MITF in the melanoma cell lines." (PMID 33202765, 2020). "Consistently, MITF has been reported to downregulate ShcD expression by directly binding to at least five sites of the genomic locus, suggesting that the MITF/ShcD axis is a critical regulator of invasiveness phenotypes of melanoma cells." (PMID 33202906, 2020). "When mouse melanoma cells promote melanogenesis, they are activated by α-MSH in the order of protein kinase A (PKA), cAMP response element binding (CREB), and protein microphthalmia-associated transcription factor (MITF)." (PMID 32120828, 2020). "Thereby, low levels of MITF correlate with a worse prognosis for melanoma patients." (PMID 32858889, 2020). "Indeed, in vitro and in vivo experiments demonstrated that antagonistic functions of EMT-TFs in melanoma at least partly rely on their differing transcriptional regulation of MITF expression." (PMID 32759677, 2020). "Indeed, PTGS2 silencing in human and murine melanoma cells resulted in decreased melanogenesis, as well as MITF expression." (PMID 33121001, 2020). "Consequently, any reduction in MITF expression should affect surface antigen presentation and recognition of melanoma cell recognition by the immune system." (PMID 33276788, 2020). "Given that β-catenin could facilitate the proliferation and metastasis of melanoma in an MITF-dependent manner, MITF probably mediates the effect of β-catenin on BRAFi therapy in melanoma patients." (PMID 32532957, 2020). "Moreover, lysoPA (LPA), which is produced by the phospholipase A2 (PLA2)-catalyzed deacylation of PA, was reported to stimulate melanoma invasion in 2D and 3D assays and to induce MITF degradation." (PMID 33121001, 2020). "Comprehensive transcriptome analysis reveals that MITF is involved in melanoma progression." (PMID 33293474, 2020).
melanoma (continued). "Importantly, BRN2 additionally contributes to melanoma progression through regulation of the master melanocytic transcriptional regulator MITF." (PMID 32632141, 2020). "Subpopulations of cells showing different MITF cellular levels have been detected in melanoma, some showing high MITF levels, which were highly differentiated and proliferative, and others with low MITF levels, exhibiting a high invasive and metastatic potential." (PMID 32013263, 2020). "In melanoma where GDF-15 expression is induced by oncogenic V600EB-Raf and by microphthalmia-associated transcription factor (MITF), GDF-15 may be involved in angiogenesis." (PMID 32508832, 2020). "Additionally, miR-26a and miR-101 have been demonstrated to be capable of inhibiting the invasion and proliferation of melanoma cells by targeting MITF." (PMID 32013263, 2020). "However, the overexpression of MITF has also been demonstrated to drive resistance, indicating a complex function of MITF in the resistance of melanoma to targeted therapy." (PMID 32532957, 2020). "However, in our MITF+ study group, all nodular melanomas were first diagnosed melanomas, identified during dermatological screening with digital follow-up or clinical examination." (PMID 32054529, 2020). "MITF represents a major coordinator of melanoma cell biology." (PMID 33396270, 2020). "The M isoform of MITF (MITF-M) is one of the major players affecting melanoma phenotype." (PMID 31624899, 2020). "Finally, we briefly discuss the role of MITF in kidney cancer, where it also plays a key role, and in immune cells, establishing MITF as a central mediator in the regulation of immune responses in melanoma and other cancers." (PMID 33276788, 2020). "MITF is one of the critical regulators of melanocyte differentiation and melanoma formation." (PMID 33628737, 2020). "Around 50% of the MITFBSs have been reported to locate in a 10 Kb segment around the transcription start sites (TSSs) in the melanoma cell line 501Mel, while more distant MITF bound enhancers, such as one −67 Kb away from the MET gene, have also been shown to be clinically relevant." (PMID 32605315, 2020). "Reciprocally, we demonstrated that MITF expression increased in AC-overexpressing melanoma cells." (PMID 32858889, 2020). "Suppression of MITF was also associated with increased expression of ligands synergizing with EGFR activation, and autocrine EGF-EGFR circuit was observed in the cultures of resistant melanoma cell lines." (PMID 31936151, 2020). "Mir-137 can inhibit the migration and invasion of melanoma cells 45–47 by targeting various mRNAs such as PIK3R3, TBX3, c-Met, YB1, EZH2, and MITF, and inhibit the proliferation and promote the apoptosis of melanoma cells by competitive binding to genes such as SLC1A5, GLO1, CDK6, etc.." (PMID 33194692, 2020). "SL metabolism could also modulate MITF levels by acting on signalling pathways known to regulate its expression in melanoma cells." (PMID 32858889, 2020). "MITF is the ‘master regulator’ of differentiation, survival and proliferation of normal melanocytes and is critical in controlling proliferation, migration and invasion of melanoma cells." (PMID 32054529, 2020). "Thus, MITF K243 status is a major determinant of melanoma tumorigenicity as well as melanocyte development." (PMID 32531202, 2020).
melanoma (continued). "Of importance, heterogeneous MITF expression has been detected in circulating melanoma cell clusters, consistently with the phenotypic heterogeneity described in breast cancer CTCs (circulating tumor cells), where a partial EMT state sustains their migratory capacity." (PMID 32759677, 2020). "On the other hand, MITF loss was shown to predict early resistance to targeted therapies, including BRAF inhibitors, and seems to be a common event in acquired resistance to BRAF inhibitors in melanoma." (PMID 32605090, 2020). "In melanoma, BRAF and MEK inhibitors can induce an upregulation of the transcription factor PAX3, which in turn stimulates the expression of the microphthalmia-associated transcription factor (MITF), ultimately promoting cell survival." (PMID 33291749, 2020). "We therefore asked whether the status of K243 would affect melanoma growth by stably expressing HA-tagged MITF WT and the K243R and K243Q mutants in the poorly tumorigenic 501mel human melanoma cell line." (PMID 32531202, 2020). "Understanding the normal and pathophysiological roles of MITF and related transcription factors may provide important clinical insights into melanoma therapy." (PMID 30705290, 2019). "Apoptosis of malignant melanoma was induced by functional inhibition of MITF." (PMID 30084054, 2019). "The MITF transcription factor is also an important factor regulating EMT in melanoma." (PMID 31514305, 2019). "MITF is the master regulator of melanocyte development and regulates multiple cellular processes, including promoting survival, differentiation and proliferation, and suppressing senescence and melanoma invasion." (PMID 30787281, 2019). "In 2005, MITF was identified as a ‘lineage survival oncogene’ in human melanoma, with significant amplification in metastatic stage and correlated with decreased overall survival in melanoma patients." (PMID 31547367, 2019). "Thus, the fact that the MAPK pathway regulates MITF expression and function is critical, considering that melanoma patients are treated with BRAF and MEK inhibitors (MAPKi)." (PMID 30277012, 2019). "Moreover, the dependency of TFIIH-CAK on the melanocyte master regulator MITF or its structural homolog c-MYC extends the conceptional idea of a CDK7-targeted treatment approach to melanoma far beyond super-enhancers as determinants of oncogenesis." (PMID 30651597, 2019). "Therefore, we chose to query the direct effects of GH on MITF expression and activity towards conferring chemoresistance in melanoma." (PMID 31547367, 2019). "Furthermore, when BRAF-mutant melanomas are treated with vemurafenib (a BRAFi), the MITF-PGC1α axis is up-regulated, which leads to increased mitochondrial respiration and scavenging of reactive oxygen species (ROS)." (PMID 30971321, 2019). "We have shown that MITF is involved in regulating this response in melanocytes and melanoma cells." (PMID 30705290, 2019). "In addition to its involvement in proliferation, miR‐101 inhibits the invasion of melanoma cells, likely due to the downregulation of its target MITF and EXH2 genes." (PMID 30499222, 2019). "This suggests that MITF has pro-survival activity in melanoma progression." (PMID 31717496, 2019). "Therefore, we present in vitro, in vivo, and in silico evidence which strongly implicates the GH–GHR axis in inducing chemoresistance in human melanoma by driving MITF-regulated and ABC-transporter-mediated drug clearance pathways." (PMID 31547367, 2019). "However, our model predicts that any intermediate state can exist and indeed in tumours BRN2 are also found significantly co‐expressed with MITF in individual melanoma cells; this can be seen in histology as well as by single‐cell gene expression analysis." (PMID 30277012, 2019). "In this context, both upregulation and downregulation of MITF expression may confer an advantage for melanoma cells treated with targeted therapeutics." (PMID 31461993, 2019).
melanoma (continued). "Analysis of biopsies from BRAFV600E melanoma patients following relapse with vemurafenib, or combination of dabrafenib and trametinib revealed upregulation of several lineage-specific transcription factors including MITF." (PMID 31040916, 2019). "Also, silencing MITF expression in melanoma cells has been previously shown to result in faster migration." (PMID 31514305, 2019). "Hence, we sought to assess NER in transcriptionally homeostatic melanoma cells with different expression levels of constitutive MITF." (PMID 30651597, 2019). "However, high expression levels of MITF have also been shown to either drive reversible drug resistance or to maintain drug resistance in melanoma." (PMID 31118886, 2019). "MITF is also the main transcriptional regulator of melanoma markers Tyrosinase and Melan-A/MART1." (PMID 30674989, 2019). "Moreover, the expression of microphthalmia-associated transcription factor (MITF), a well-known PGC-1α transactivator in melanoma cells, was upregulated in cells incubated with HLA-B,C-specific mAb B1.23.2." (PMID 31454998, 2019). "The role and importance of localisation and heterodimerization of MITF, TFEB and TFE3 in melanoma cells remains to be explored and may reveal why MITF regulates a distinct set of genes compared to the other factors." (PMID 30705290, 2019). "The complex regulation of MITF expression in the highly heterogenous tumor population is affected by multiple upstream signaling pathways, genetic and epigenetic alterations, as well as by the melanoma microenvironment." (PMID 31547367, 2019). "Interestingly, melanoma cells display varying amounts of MITF, which can be used to identify different subpopulations within melanoma lesions." (PMID 30823658, 2019). "Furthermore, MITF is required for the survival of drug‐addicted resistant melanomas and MITF upregulation is found in up to 23% of melanomas progressed on treatment." (PMID 30277012, 2019). "In melanoma, it was observed that MITF is both regulated by and regulates miRNAs." (PMID 30499222, 2019). "In vitro silencing of FBXW7 in melanoma considerably enhanced MITF/PGC-1 signaling contributing to the augmentation of mitochondrial transcription program and may result in poor outcomes for the patients." (PMID 30791487, 2019). "Importantly, we successfully identified two melanoma-specific markers, i.e., MITF (Microphthalmia-associated transcription factor) and MLANA (Melanoma antigen recognized by T-cells) in the exosome-exposed MSCs." (PMID 31681332, 2019). "MicroRNA miR‐137 acts as tumor suppressor; in fact, the expression of miR‐137 in melanoma leads to the inhibition of the proliferation and invasion by the downregulation of its targets, including MITF, c‐Met, Y‐box‐binding protein 1 (YB‐1) and enhancer of zeste homolog 2 (EZH2)." (PMID 30499222, 2019). "Additionally, the application of excess cholesterol, which can be transported by SR-BI, induced pigmentation and upregulation of MITF in human melanocytes and melanoma cells." (PMID 30823658, 2019). "MITF plays a central role in regulating melanocytic lineage as well as phenotype switching in melanoma and elicits a tightly regulated survival advantage to melanoma, especially under therapeutic challenge." (PMID 31547367, 2019). "Importantly, depletion of p300 and MITF in melanoma cells has been show to induce cell cycle arrest and a senescent phenotype." (PMID 30674989, 2019). "The discrepancies between MITF function in melanoma may be explained by the temporal differences in the analysis." (PMID 31416288, 2019). "Besides classic EMT markers, we also evaluated mRNA levels of FRA-1 and MITF transcription factors—both of which are important factors of melanoma progression—and their correlation with migratory and proliferative capacity." (PMID 31514305, 2019).
melanoma (continued). "Transcription factors like MITF can play a critical role in melanoma." (PMID 31569419, 2019). "Currently, the National Comprehensive Cancer Network (NCCN) reports that BAP1 testing may be warranted in specific cases, along with testing for other melanoma-predisposing genes like CDK4, MITF and TERT." (PMID 31382929, 2019). "As mutations in high-susceptibility genes greatly increase risk of melanoma development, individuals carrying CDKN2A, CDK4, BAP1, POT1, or MITF mutations should be educated on the importance of melanoma prevention and early detection and should undergo regular medical skin examination." (PMID 31717496, 2019). "Since eIF2α phosphorylation is a key determinant of melanoma phenotype, our observations are consistent with elevated glucose uptake under hypoxia contributing to the maintenance of MITF expression." (PMID 31207090, 2019). "Choosing SCM as the microenvironment for melanoma cells was crucial with transcriptomic analysis that serum present in the medium drastically reduces expression of MITF-M and 74 MITF-dependent genes, including TYR, DCT, and MLANA." (PMID 31354817, 2019). "As such, the low levels of SDHB in MITF‐low cells may contribute to disease progression in melanoma." (PMID 31207090, 2019). "On the other hand, other studies, including our own, have shown that melanoma cells may lose MITF expression during acquisition of drug resistance." (PMID 31461993, 2019). "Therefore, our results implicate the JAK2-STAT5 as well as the SRC pathway as the principal molecular mediators of GH-mediated upregulation of MITF expression and activity in melanoma." (PMID 31547367, 2019). "Previous work has established that MITF is a key regulator of melanoma phenotype." (PMID 31207090, 2019). "Moreover, MITF repression during starvation-induced translational reprogramming has been shown to correlate with drug and immunotherapy resistance of melanoma cells." (PMID 31118886, 2019). "Furthermore, it has been demonstrated that increased MITF expression renders melanoma cells resistant to BRAF pathway inhibition." (PMID 31416288, 2019). "To determine if this effect on autophagosomal formation is specific to melanoma cells, we investigated whether knocking down MITF also affects autophagy in human primary normal epidermal melanocytes (NHEM)." (PMID 30705290, 2019). "The MITF-PGC1α axis is a master regulator of mitochondrial function in melanomas." (PMID 30971321, 2019). "This tumoral heterogeneity renders a high level of plasticity to melanoma tumors to switch between phenotypes of proliferation to invasion to stemness, along a high to low MITF gradient, thereby abetting the characteristic extreme therapy refractoriness of melanoma." (PMID 31547367, 2019). "Also, because LDE-EA inhibited melanin synthesis and tyrosinase expression, we evaluated if LDE-EA is reduced the production of cAMP, which induces the expression of MITF, in B16 melanoma cells." (PMID 30695994, 2019). "In vivo, melanoma cells transition though distinct phenotypic states in response to a changing microenvironment, and most notably can switch between invasive and proliferative phenotypes characterized by low and high levels of MITF activity respectively." (PMID 31207090, 2019). "It was suggested that MITF can be activated by the MAPK pathway in malignant melanoma development." (PMID 31717496, 2019). "Given the importance of MITF in determining the phenotypic state of melanoma cells, there is considerable interest in understanding how it might be regulated by the intra‐tumor microenvironment." (PMID 31207090, 2019). "The role of miR‐211 in melanotic melanoma cells is to contribute to a ‘normalization program’ activated by the inhibition of the ERK pathway: the resulting de‐repression of MITF promotes a switch from glycolysis to oxidative phosphorylation involving PGC1alpha and mitochondrial biogenesis." (PMID 30499222, 2019).